ABCF1 (ATP binding cassette subfamily F member 1)
Description:
Isoform 2 is required for efficient Cap- and IRES-mediated mRNA translation initiation. Isoform 2 is not involved in the ribosome biogenesis.
Synonyms: ABC50; EST123147; ABC27
Tractability: Small molecule: a structure with a bound ligand is known. PROTAC: ubiquitination databases record sites on it; its protein half-life has been measured.
Gene: Protein-coding gene on chromosome 6 (30,571,393 to 30,597,179, forward strand). Ensembl gene ENSG00000204574.
Subcellular location: Cytoplasm (Isoform 2); Nucleus, nucleoplasm; Nucleus envelope
Subcellular location (Human Protein Atlas): Cytosol
Pathways (Reactome):
Transport of small molecules: ABC-family protein mediated transport
Gene Ontology:
Molecular function: protein binding; RNA binding; ATP binding; translation factor activity, RNA binding; ATP hydrolysis activity
Biological process: inflammatory response; translation
Cellular component: cytoplasm; cytosol; membrane; nuclear envelope; nucleoplasm
Genetic constraint (gnomAD): Loss-of-function variants: 72 observed, 126.98 expected, observed/expected ratio (o/e) 0.57, 90% interval 0.47 to 0.69. The upper end of that interval is the gene's LOEUF score, 0.69, which puts it in group 2 of 6, group 1 being the genes least tolerant of losing a copy. Missense variants: 776 observed, 1,079.7 expected, observed/expected ratio (o/e) 0.72, 90% interval 0.68 to 0.76. Synonymous variants: 343 observed, 400.89 expected, observed/expected ratio (o/e) 0.86, 90% interval 0.78 to 0.94.
Homologues: Orthologues: pig ABCF1 (97% identical), macaque ABCF1 (97% identical), chimpanzee ABCF1 (96% identical), dog ABCF1 (96% identical), rabbit ABCF1 (95% identical), rat Abcf1 (91% identical), mouse Abcf1 (91% identical), guinea pig ABCF1 (82% identical), tropical clawed frog abcf1 (76% identical), zebrafish abcf1 (73% identical), Drosophila melanogaster CG1703 (54% identical), Caenorhabditis elegans abcf-1 (42% identical). Paralogues in human: ABCF3 (34% identical), ABCF2 (29% identical).
Diseases named in the same sentence as ABCF1 in open-access papers:
ABCF1 is named in the same sentence as 34 diseases in open-access papers, as found by Europe PMC text mining. Sharing a sentence is not in itself a finding about the gene and the disease. The quoted sentences say what the papers report.
hepatocellular carcinoma (6 papers, 2022 to 2025). A malignant tumor that arises from hepatocytes. "Recent studies have revealed that non‐histone lactylation of ABCF1 plays a significant role in the growth and metastasis of hepatocellular carcinoma (HCC)." (PMID 41020792, 2025). "ABCF1 K430la, which is upregulated in hepatocellular carcinoma, alters the protein conformation and exposes the nuclear localization sequence (NLS), guiding ABCF1 into the nucleus and activating the HIF1 signaling pathway." (PMID 40994548, 2025). "In hepatocellular carcinoma cell line (HepG2), ABCF1 K430la facilitates tumor progression by stimulating the expression of HIF1A and its downstream molecules, enhancing lactate production." (PMID 40994548, 2025). "Furthermore, ABCF1 has been shown to be overexpressed in hepatocellular carcinoma." (PMID 36371147, 2022). "ABCF1 K430la mediates its nuclear translocation, upregulates KDM3A expression, and enhances H3K9me2 demethylation, activating the HIF1A pathway to promote hepatocellular carcinoma progression." (PMID 40994548, 2025).
breast carcinoma (4 papers, 2012 to 2024). "Another ABC protein found to be up-regulated in breast cancer is ABCF1, which has now been used as part of a six-gene signature that can be used to predict the outcome of breast cancer in patients." (PMID 32587767, 2020). "It is part of the coding region of the ATP-binding cassette subfamily F member 1 (ABCF1), which is over expressed in breast cancer." (PMID 22438871, 2012).
autoimmune pancreatitis (3 papers, 2017 to 2024). "Polymorphism in the ABCF1 gene has also been associated with autoimmune pancreatitis in the Japanese population." (PMID 28542262, 2017). "ABCF1 is an ABC transporter family protein that has been shown to regulate innate immune response and is a risk gene for autoimmune pancreatitis and arthritis." (PMID 28542262, 2017).
liver cancer (2 papers, 2023 to 2024). An epithelial or non-epithelial malignant neoplasm that arises from the liver. "Lactation of lysine has recently been identified in liver cancer, which occurs mainly on two tumor‐associated proteins, USP14 and ABCF1, which promote the development of liver cancer and lung metastasis." (PMID 39184862, 2024). "It has been reported that ABCF1 is overexpressed in liver cancer; is a liver tumor fetal protein that promotes chemotherapy resistance, epithelial-mesenchymal transition and tumor stem cell differentiation in liver cancer cells; and has potential as a therapeutic target." (PMID 36932399, 2023).
rheumatoid arthritis (2 papers, 2020 to 2023). A chronic, systemic autoimmune disorder characterized by inflammation in the synovial membranes and articular surfaces. "The original discovery that ABCF1 expression was regulated by TNF-α stimulation suggested a link to immune responses, although no differential expression patterns were observed for synoviocytes from healthy individuals or those with rheumatoid arthritis." (PMID 33042865, 2020).
Sepsis (2 papers, 2020). Sepsis is defined as life-threatening organ dysfunction caused by a dysregulated host response to infection. "Complementary to dsDNA sensing, immune modulation mediated by ubiquitin-conjugating activities of ABCF1 have been defined in the context of macrophage polarization and immune responses linked to interferon-β production and tolerance important in mouse models of sepsis." (PMID 33042865, 2020). "Using in vitro an in vivo model systems, ABCF1 was implicated in polarizing pro-inflammatory macrophages to an anti-inflammatory/tolerant macrophage phenotype with direct involvement in shifting the systemic inflammatory response syndrome to a endotoxin tolerance phase in sepsis." (PMID 33042865, 2020).
Anxiety (1 paper, 2021). Intense feelings of nervousness, tension, or panic often arise in response to interpersonal stresses. "No differential DNA methylation was associated with PND alone; however, differential DNA methylation was observed in children exposed to comorbid PND with anxiety symptoms compared with healthy controls in ABCF1 (log twofold change − 0.2), but not after stratification by sex of the child." (PMID 33845866, 2021).
autism (1 paper, 2021). Persistent deficits in social interaction and communication and interaction as well as a markedly restricted repertoire of activity and interest as well as repetitive patterns of behavior. "Altered methylation of ABCF1 has also been seen to be associated with autism in an in silico analysis multi-omics data analysis including frontal cortex samples." (PMID 33845866, 2021).
autoimmune disease (1 paper, 2020). A disorder resulting from loss of function or tissue destruction of an organ or multiple organs, arising from humoral or cellular immune responses of the individual to their own tissue constituents. "Similarly, ABCF1 plays a role in the regulation of inflammatory processes and alterations in ABCF1 are linked with autoimmune diseases as well." (PMID 33334016, 2020).
bladder cancers (1 paper, 2023). "Furthermore, Kaplan‒Meier survival analysis showed that high expression of ABCF1 was associated with poor prognosis in patients with bladder cancer." (PMID 36932399, 2023). "High expression of ABCF1 was correlated with poor overall survival in bladder cancer patients (P < 0.001)." (PMID 36932399, 2023). "In our study, we explored the differential expression of ABCF1 in bladder cancer and normal bladder tissues based on bioinformatic analysis and immunohistochemical results." (PMID 36932399, 2023). "A survival analysis of the prognostic information of 60 bladder cancer patients using immunohistochemical results showed that the higher the expression of ABCF1, the worse the prognosis of the patient was (P = 0.03)." (PMID 36932399, 2023). "In this study, we explored the expression of ABCF1 in bladder cancer and studied the prognosis and molecular function of ABCF1." (PMID 36932399, 2023). "The relationship between ABCF1 expression and bladder cancer progression was analyzed using the GSE13507 dataset." (PMID 36932399, 2023). "ABCF1 was upregulated in bladder cancer, and the high expression of ABCF1 was closely related to sex (P = 0.00056), grade (P = 0.00049), T stage (P = 0.00007), and N stage (P = 0.0076)." (PMID 36932399, 2023). "Univariate and multivariate Cox regression analyses indicated that ABCF1 expression was an independent prognostic factor in bladder cancer." (PMID 36932399, 2023). "In our study, bioinformatics analysis of ABCF1 datasets from public databases revealed that the expression of ABCF1 was significantly increased in bladder cancer compared with normal bladder tissue." (PMID 36932399, 2023). "This is consistent with our results using qRT‒PCR and Western blotting to validate ABCF1 mRNA expression levels in bladder cancer cell lines." (PMID 36932399, 2023). "Western blotting was used to detect the expression of ABCF1 in bladder cancer cell lines and normal bladder epithelial cells." (PMID 36932399, 2023). "The results showed that the expression level of ABCF1 mRNA was significantly higher in most bladder cancer cell lines than in the normal bladder epithelial cell line SV-HUC-1." (PMID 36932399, 2023). "Thus, we are planning to perform a series of experiments to reveal the prognostic value of ABCF1 in bladder cancer." (PMID 36932399, 2023). "Overall, these results suggest that ABCF1 is elevated in bladder cancer." (PMID 36932399, 2023). "In addition, we also evaluated the effect of ABCF1 expression on the survival of bladder cancer patients by univariate and multivariate Cox regression analyses." (PMID 36932399, 2023). "Our findings suggest that high expression of ABCF1 is a factor in poor prognosis of bladder cancer patients and may serve as a potential target for future therapeutic strategies." (PMID 36932399, 2023). "Next, we showed that ABCF1 is highly expressed in bladder cancer tissue through an IHC assay, and we performed a survival analysis of the prognostic information of bladder cancer patients, which showed that the higher the expression of ABCF1, the worse the prognosis of the patients was." (PMID 36932399, 2023). "ABCF1 was differentially expressed in 17 cancer types, including bladder cancer." (PMID 36932399, 2023). "In addition, univariate and multivariate Cox regression analyses showed that high ABCF1 expression was an independent factor for poor prognosis in bladder cancer patients." (PMID 36932399, 2023). "This study suggests that ABCF1 may serve as a novel biomarker for predicting poor prognosis in bladder cancer." (PMID 36932399, 2023). "Moreover, the protein expression of ABCF1 in bladder cancer tissues was significantly higher than that in paired adjacent noncancer tissues." (PMID 36932399, 2023). "This suggests that bladder cancers with high ABCF1 expression may be more likely to progress to an advanced stage." (PMID 36932399, 2023).
bladder cancers (continued). "In conclusion, our study found that ABCF1 could serve as a prognostic marker and potential therapeutic target for bladder cancer." (PMID 36932399, 2023). "We analyzed the prognostic value of ABCF1 expression in bladder cancer using the GSE13507 dataset." (PMID 36932399, 2023). "Therefore, ABCF1 expression is closely related to the progression of bladder cancer and can be used as a potential indicator of poor prognosis and a therapeutic target for bladder cancer." (PMID 36932399, 2023). "However, the role of ABCF1 in bladder cancer is poorly understood." (PMID 36932399, 2023). "Therefore, we aimed to explore whether ABCF1 could serve as a prognostic target in bladder cancer patients through bioinformatics analysis." (PMID 36932399, 2023). "Then, we further evaluated the expression level of ABCF1 in bladder cancer using TCGA and GSE13507 data and found that the ABCF1 mRNA expression level was significantly increased in bladder cancer tissue compared with normal bladder tissue." (PMID 36932399, 2023). "However, the prognostic role of ABCF1 in bladder cancer remains unclear." (PMID 36932399, 2023).
breast tumours (1 paper, 2022). "Nevertheless, we showed that decreased ABCF1 gene expression in breast tumours is associated with chemosensitivity." (PMID 35631534, 2022).
clear cell renal cell carcinoma (1 paper, 2021). "However, there is no clear cell renal cell carcinoma vs normal in the five datasets of ABCF1.The result showed that ABCG1 was highly overexpressed in all datasets." (PMID 33825659, 2021).
colon carcinoma (1 paper, 2020). "Statistical analysis comparing ABCF1 reduction and siRNA control treated HBEC-6KT confirmed ABCF1 gene was down-regulated which was associated with only one other significantly differentially expressed (up or down) gene, C12orf75, which encodes overexpressed in colon carcinoma-1 (OCC-1) protein." (PMID 33042865, 2020).
colorectal cancer (1 paper, 2022). A primary or metastatic malignant neoplasm that affects the colon or rectum. "ABCF1 also plays an important role in the chemoresistance of colorectal cancer cells with microsatellite instability to 5-fluorouracil." (PMID 35722625, 2022).
Ewing sarcoma (1 paper, 2019). A small round cell tumor that lacks morphologic, immunohistochemical, and electron microscopic evidence of neuroectodermal differentiation. "Consistently, as observed in Ewing sarcoma cells, the functions of IGF2BP3 can be limited by the mRNA expression of ABCF1, which is a partner transcript of IGF2BP3." (PMID 32010687, 2019).
melanoma (1 paper, 2022). A malignant, usually aggressive tumor composed of atypical, neoplastic melanocytes. "The role of ABCF1 in melanoma has not been reported, but in our PPI analysis, we found that ABCF1 was indirectly correlated with ELAVL1, which may be the mechanism how it participates in melanoma progress." (PMID 35722625, 2022).
renal carcinoma (1 paper, 2021). A carcinoma arising from the epithelium of the renal parenchyma or the renal pelvis. "There are eight, five, and eight datasets of ABCC3, ABCF1, and ABCG1 for renal cancer, respectively." (PMID 33825659, 2021).
schizophrenia (1 paper, 2012). A major psychotic disorder characterized by abnormalities in the perception or expression of reality. "The most central (‘hub’) gene in this network, ABCF1, is cis-regulated, which means that nearby genetic variation indirectly/directly regulates this schizophrenia-associated gene expression network." (PMID 22761806, 2012). "The most highly connected intramodular hub gene in this module (ABCF1), is located in, and regulated by the major histocompatibility (MHC) complex, which is intriguing in light of the fact that common allelic variants from the MHC region have been implicated in schizophrenia." (PMID 22761806, 2012).
ZIKV infection (1 paper, 2020). "Our proteomic data implicate ABCF1 as a potential retinal target protein during ZIKV infection." (PMID 32850779, 2020).
cancer (10 papers, 2012 to 2025). A tumor composed of atypical neoplastic, often pleomorphic cells that invade other tissues. "ABCF1 is a transporter of molecules through membranes, and has been associated to drug resistance and the development of some types of cancer." (PMID 22438871, 2012). "ABCF1, a multidrug resistance gene, confers resistance of cancer cells to a range of anti-cancer agents." (PMID 39423857, 2025). "In cancer, related reports show that there may be some correlation between high expression of ABCF1 and the metastatic potential of soft tissue tumors." (PMID 36932399, 2023). "In addition, we also found that many cancer-related genes interact with ABCF1 through the PPI network." (PMID 36932399, 2023). "Previous studies have shown that overexpression of ABC transporters (such as ABCF1) not only altered the chemoresistance profile of cancer cells, but also affected the biological characteristics, such as morphology and migration, which are critical factors in cancer development." (PMID 34631561, 2021). "ABCF1 is a hepatic oncofetal protein that modulates migration, epithelial–mesenchymal transition (EMT), and cancer stemness properties and is considered a novel potential therapeutic target for HCC treatment." (PMID 36557005, 2022).
tumor (5 papers, 2023 to 2025). "Due to their involvement in tumor metastasis and progression, ABCF1 and USP14 were discovered." (PMID 39968078, 2025). "In liver cancer, ABCF1 K430la activates the KDM3A-H3K9me2-HIF1A axis, with K430Q mutants displaying greater tumor growth and metastasis in mouse models." (PMID 40994548, 2025).
infection (3 papers, 2022 to 2024). The state of being infected such as from the introduction of a foreign agent such as serum, vaccine, antigenic substance or organism. "The differentially expressed proteins post-infection include Akap1, Prkaca, Prkab2, Acaca, Acacb, Aka1, Abcf1, Synj1, Braf, Vcl, and Fhod3, which involve insulin receptor signal, glucagon signal pathway, AMPK signal pathway, and Hippo signal pathway." (PMID 35313969, 2022).
ABCF1 also shares sentences with these, for which no sentence is quoted: Arthritis (2 papers); celiac disease (1); cervical cancer (1); diabetes (1); endotoxemia (1); gout (1); leukemia (1); lung carcinoma (1); ovarian carcinoma (1); prostate carcinoma (1); renal cell cancer (1); systemic inflammatory response syndrome (1).